JUNB (JunB proto-oncogene, AP-1 transcription factor subunit)
Diseases named in the same sentence as JUNB in open-access papers (continued):
Sharing a sentence is not in itself a finding about the gene and the disease.
seborrheic dermatitis (1 paper, 2018). A chronic, inflammatory skin disorder that affects the scalp, central face and skin folds; it is characterized by scaling and itching. "Interestingly, this murine model with JunB deficiency in K14 expressing basal epidermal progenitors closely mirrors human seborrheic dermatitis clinically and histologically." (PMID 30143626, 2018). "JunB cKOs suffering from seborrheic dermatitis revealed enlarged sebaceous glands most likely due to the lack of fate restriction of epidermal progenitor cells towards sebocytes or to hyperproliferation." (PMID 30143626, 2018). "Likewise human seborrheic dermatitis, the JunB cKOs displayed typical histological features including sebaceous gland hyperplasia, epidermal hyperplasia with signs of spongiosis (edema between epidermal cells), parakeratosis and a persistence of infiltrating inflammatory cells." (PMID 30143626, 2018).
status epilepticus (1 paper, 2016). Status epilepticus is defined as a continuous seizure lasting more than 30 min, or two or more seizures without full recovery of consciousness between any of them. "Kainic acid induces recurrent seizures, and the selected time point (i.e., 6 h) after the induction of status epilepticus enabled us to observe not only late-response genes but also early-response genes (e.g., Fos, JunB, FosB, Egr2, Egr4)." (PMID 25636686, 2016).
steatosis (1 paper, 2020). Increased lipid within the cytoplasm of cells. "Of the top-ranked 10 genes, two genes (CYP7A1 and PEG10) were significantly up-regulated in both steatosis and NASH patients, while eight genes (FOSB, FOS, IL6, GADD45G, MYC, SLITRK3, JUNB, and IGFBP2) were significantly down-regulated." (PMID 33324350, 2020).
testicular cancer (1 paper, 2025). A primary or metastatic malignant neoplasm that affects the testis. "Finally, there is also a limited number of studies mentioning JUNB in testicular cancer." (PMID 41020863, 2025).
thoracic aortic aneurysm (1 paper, 2024). An aneurysm formed in the wall of the proximal portion of the descending aorta proceeding from the arch of the aorta. "JunB is one of the main activator protein-1 (AP-1) proteins in mammalian cells and has been identified as an essential contributor to the development of vascular diseases such as thoracic aortic aneurysm and aortic dissection." (PMID 38826134, 2024).
tuberculous pleurisy (1 paper, 2021). "A total of eight possible biomarkers of tuberculous pleurisy were screened (RPL17, UBA7, NDUFB8, UQCRFS1, JUNB, PSMC4, PHPT1, and MAPK11)." (PMID 34925441, 2021).
type 2 diabetes (1 paper, 2017). "These signaling pathways contained the significant gene regulatory network of transcript factors families for type 2 diabetes including SP1, NFIC, ZFP161, and FOS, JUND, JUNB." (PMID 28179884, 2017).
urothelial carcinoma (1 paper, 2025). A malignant neoplasm derived from the transitional epithelium of the urinary tract (urinary bladder, ureter, urethra, or renal pelvis). "JUNB was found to be downregulated following CD138 silencing in urothelial carcinoma cell lines, an outcome that impaired survival and led to induction of apoptosis." (PMID 41020863, 2025). "In UM-UC-3 human urothelial carcinoma cells, FGF2 was found to exhibit anti-proliferative activity by affecting the intracellular transcriptional activity via the modulation of JUNB and FosB proto-oncogene (FOSB)." (PMID 41020863, 2025).
Von Hippel–Lindau syndrome (1 paper, 2025). "The significance of JUNB in RCC emergence and its relation to VHL were further reinforced by a later study in which a VHL variant, VHLX214L, was found to be associated with a Type 2A VHL syndrome, a subtype of VHL that increases RCC development risk." (PMID 41020863, 2025).
yang deficiency (1 paper, 2022). Yang deficiency is a concept from traditional Chinese medicine. "The symptomatic gene targets for Yang deficiency (KAT2B, NFKB2, CREBBP, GTF2H3) or Yin deficiency (JUNB, JUND, NGLY1, TNF, RAF1, PPP1R15A) were potentially discovered." (PMID 35341155, 2022).
tumor (160 papers, 2007 to 2026). "Findings revealed heightened regulon activities of JUNB in the immune exclusion tumor area, which is implicated in tumorigenesis by regulating cell proliferation, differentiation, senescence, and metastasis." (PMID 39505867, 2024). "Previous reports have associated high levels of JUNB in circulating tumor cells with poor prognosis." (PMID 37240946, 2023). "Nevertheless, stromal loss of JunB was found to promote the infiltration of neutrophil in tumor metastasis." (PMID 37731821, 2023). "This review summarizes the physiological function of JunB, its immune regulatory function, and its contribution to tumorigenesis, especially focusing on its regulatory mechanisms within tumor-associated immune processes." (PMID 37731821, 2023). "The top motif enriched in upregulated peaks involved many transcription factors associated with tumor metastasis, such as AP-1 family members Fra1, JunB, Atf3, and Fos." (PMID 36579891, 2022). "Yet, despite the high efficiency of anti-Ly6G antibody in the initial phase, at later stages of tumor progression depletion was technically impossible, at least with our approach, most likely due to the vast neutrophil numbers in JUNB-deficient mice." (PMID 34282521, 2021). "High constitutive activity of AP-1 family members including JUNB is a hallmark of HRS cells, but in LP cells, JUNB mutations seemingly support a tumor suppressor role." (PMID 33686198, 2021). "The transcription factor JUNB had previously been linked to invasion and metastasis but studies had largely focused on tumor cells thereby ignoring the complexity of the tumor microenvironment." (PMID 34282521, 2021). "Further study is required to examine the details of the cellular and molecular mechanisms underlying the JunB-mediated promotion of tumor invasion in HNSCC." (PMID 26754630, 2016). "In addition to IRF4 and AP‐1/JunB, the Ets transcription family has been implicated in tumor cell upregulation of CD30." (PMID 41123243, 2026). "JUNB’s role in immune TME (in the context of urological tumors) is also a major aspect of its activity since it has been found to regulate associations of the tumor cells with TAMs and other immune cells." (PMID 41020863, 2025). "Of note, all the cases with the JUNB mutation showed similarly high tumor content." (PMID 38585847, 2024). "We next asked whether JunB is expressed by microglia and infiltrating tumor-associated macrophages (TAMs) in brains of mice with MBM." (PMID 37894348, 2023). "Stromal loss of JunB in mice led to increased tumor metastasis to lung." (PMID 37731821, 2023). "TAM-mediated PCa progression is partially attributed to the aberrant expression of miR-95, and the miR-95/JunB axis could be used for cancer therapy, which confirms that tumor-associated macrophages take part in cell-to-cell communication." (PMID 37237523, 2023). "At first sight this may appear paradoxical as Mmp9 and Bv8 overexpression due to stromal JUNB loss should also have a positive impact on primary tumor growth." (PMID 34282521, 2021). "Taken together, these data indicate that the correlative expression of JunB with distinct AFs may be linked to the molecular background of tumor cells." (PMID 34007044, 2021). "Besides, the high level of JUNB in the tumor was associated with a favorable RFS." (PMID 35051313, 2022). "Association of the expressions of SRC, JUNB and FOSB as well as PD-L1 expression in tumor samples of KRAS-mutant NSCLC patients." (PMID 40599804, 2025). "We report a spatially regulated dichotomy in the AP1 transcriptional programs (JUNB vs. cJUN) in PDAC subtype plasticity via both tumor cell intrinsic and extrinsic mechanisms." (PMID 39762215, 2025). "The progression of fibrosis around the tumor nodule was increased by the overexpression of JUNB, which increased the positivity of Sirius Red." (PMID 40253402, 2025).
tumor (continued). "Differential expression of key metastasis-associated genes (CDH1, JUNB, and DUSP5) confirmed the scaffold’s ability to recapitulate important molecular features of the tumor microenvironment." (PMID 40558895, 2025). "FTO‐mediated m6A demethylation increases the levels of the transcription factors c‐Jun, JunB, and C/EBPβ in tumor cells, which alters glycolytic metabolism, impairs CD8+ T cell function, and inhibits tumor progression." (PMID 39802639, 2025). "Taken together, the data support a role for elevated AP-1 transcriptional activity in driving tumor progression and underscore the clinical relevance of JUNB and cJUN as prognostic markers in EAC." (PMID 40701988, 2025). "The immunohistochemistry images revealed that SRC was located mainly in the cytoplasm of the tumor cells; JUNB and FOSB were located mainly in the cell nucleus; and PD-L1 was located mainly in the cytoplasm and nucleus of the tumor cells." (PMID 40599804, 2025). "Differential gene expression highlighted immune regulation pathways and transcriptional networks centered on JUN, JUNB, and FOSB, linked to immune suppression and tumor progression." (PMID 42004296, 2025). "In bladder cancer (BCa), JUNB has been mentioned several times, mostly as a TF with tumor-promoting activity." (PMID 41020863, 2025). "The inactivation of JUNB was also shown to promote pro-invasive activity, thus crediting JUNB with a tumor suppression role in early PCa stages, which is gradually lost in later stages." (PMID 41020863, 2025). "Association of the expressions of SRC, JUNB, FOSB and PD-L1 as well as clinicopathological characteristics in tumor samples of KRAS-mutant NSCLC patients." (PMID 40599804, 2025). "While c-Jun and c-Fos act as oncogenic drivers, JunB functions as a tumor suppressor, illustrating the context-dependent duality of AP-1." (PMID 41303380, 2025). "Of note, JUNB performs tumour suppressor activity in NLPHL, supporting its regulatory connection with SPP1 restricted to cHL." (PMID 40149711, 2025). "Histological analysis of subcutaneous tumors revealed fibrous septa around the tumor because of JUNB overexpression." (PMID 40253402, 2025). "The present study examined CXCR4, JUNB, and PD-L1 at molecular and protein levels in circulating tumor cells (CTCs) derived from patients with mPCa." (PMID 38727318, 2024). "We also found the high expression of tumor suppressor gene SPINT2 at early stage and subsequent up-regulation of the oncogene JUNB, revealing an increase of metastasis potential over the tumor evolution of metabolism-type PCCs." (PMID 38407266, 2024). "JunB proto-oncogene (JunB) has bidirectional regulation and can function as an oncogene or tumor suppressor." (PMID 38032489, 2024). "Overexpression of ZIC2 induced tumor growth in vivo, with the increase of JUNB, MCSF secretion, and CD163." (PMID 37479694, 2023). "The potential significance of JunB as a therapeutic target in tumor treatment spans its involvement in inflammation regulation to its contribution to tumor development." (PMID 37731821, 2023). "Exosomes containing miR-95, when taken up by prostate cancer cell lines, promoted tumor formation by binding to JunB." (PMID 37237523, 2023). "Conducting comprehensive investigations into the role of JunB within the TME will contribute a more comprehension of tumor pathogenesis." (PMID 37731821, 2023). "JUNB has been reported to be a tumor-promoting factor in the processes of tumorigenesis and development." (PMID 37479694, 2023). "Cells expressing high JunB levels were generally polarized into anti-inflammatory, immunosuppressive, and pro-tumor microglia, while cells expressing low JunB levels were generally polarized into pro-inflammatory, anti-tumor microglia." (PMID 37894348, 2023). "Increasing evidence suggests that JunB is usually dyregulated in cancer and can perform tumor suppressive or oncogenic role depending on the cancer entity." (PMID 37731821, 2023).
tumor (continued). "To further evaluate the clinical significance of JUNB, we analyzed several cohorts and found that JUNB expression was much higher in tumor tissues than in normal tissues in both the TCGA-GC dataset and the GSE51429 dataset." (PMID 37337631, 2023). "The involvement of JunB in the tumor microenvironment (TME) of these malignancies partially aligns with its role in immune regulation." (PMID 37731821, 2023). "We searched the Human Protein Atlas for JUNB-associated negative survival analysis results and found that the protein expression of JUNB in normal samples was much higher than that in tumor samples." (PMID 37501756, 2023). "Further studies suggested that CCL2, the downstream effector of JunB, promotes ccRCC through promoting tumor angiogenesis and recruiting macrophages." (PMID 37731821, 2023). "Generally, JunB regulates cell cycle, differentiation, senescence, metabolism, and metastasis of tumor cells to affect tumor progression." (PMID 37731821, 2023). "JUNB expression was observed at all tumor sites tested with signals stronger in UTA6-JUNB cell-derived primary tumors and metastases than in UTA6-Control cell-derived primary tumors analyzed by IF and IHC." (PMID 36494864, 2022). "This led us to propose novel roles for JUNB activity in the regulation of both cell cycle and tumor progression." (PMID 36494864, 2022). "JunB is a unique factor of activator protein-1 transcription factors, appearing both as a tumor suppressor or as an oncogene relying on the cell context." (PMID 36479105, 2022). "ZFP36 is downregulated in the tumor compared with normal samples, and co‐expressed with JUN, JUNB, FOS, and FOSB, downregulation of which was associated with poor outcomes and BC progression." (PMID 35037412, 2022). "Functional experiment results supported these findings and implied the important role of JUNB in the pro-tumor proliferation effect of CAFs." (PMID 35812726, 2022). "Similar to primary tumor cells, a significant positive Pearson correlation score was also observed for JunB and VEGF, VEGFB, and IGF1 in a selected number of MM cell lines deposited in the CCLE database." (PMID 34007044, 2021). "As JUNB is a common downstream target of anti-proliferative cancer therapy, efforts have to be taken ensuring the design of tumor-specific therapies leaving JUNB levels in the tumor microenvironment unaffected." (PMID 34282521, 2021). "JUNB plays a critical role in tumor cell invasion, migration, and metastasis, both through EMT-dependent and EMT-independent pathways." (PMID 34455105, 2021). "Overall, these in vivo studies reveal that JunB and Fos exhibit a tumor suppressor function by repressing invasive disease, whereas Jun is oncogenic and increases cell proliferation." (PMID 34548912, 2021). "For example, in a mouse model of ALK+ ALCL where expression of NPM-ALK was driven in T cells by a CD4 promoter, tumour formation was only compromised when both c-Jun and JunB were knocked-out, and double knock-out cells exhibited impaired proliferation." (PMID 33413671, 2021). "We observe an enrichment for Fra1, Fra2, JunB, Atf3 and AP-1 in tumours with Gleason pattern 3 whereas tumours with Gleason pattern 4 show an enrichment for FOXA1, HOXB13 and CDX2." (PMID 34911933, 2021). "Results in tumor-cell models that allow the induction of JunB knockdown or JunB activation, respectively, corroborated the functional role of JunB in the production and secretion of these angiogenic factors (AFs)." (PMID 34007044, 2021). "Hereby, we have delineated that JunB and Fos exhibit tumor suppressor function in PCa, while Jun is oncogenic in the context of Fos loss." (PMID 34548912, 2021). "In cancer, JUNB is frequently deregulated and dependent on the cancer entity can act as tumor suppressor or oncogene." (PMID 34282521, 2021).
tumor (continued). "While the expression of the AP-1 transcription factor family member cJun was reduced in tumors compared with adjacent non-tumor tissue, the closely related family members JunB and JunD were significantly upregulated." (PMID 33738287, 2021). "In contrast to JunB, hypoxia and Hif-1α levels increase in the BM of MM patients during disease progression due to rapidly proliferating tumor cells and promote MM cell dissemination and bone destruction." (PMID 34007044, 2021). "The enhanced neutrophil infiltration especially into lungs of tumor-bearing JUNB KO mice was further confirmed by immunohistochemistry." (PMID 34282521, 2021). "Specifically, the c-Jun AP-1 family member has been implicated in tumor progression, while the JUNB and JUND played tumor suppressor role." (PMID 32079144, 2020). "It should be noted that, consistent with our observations, other studies have also reported that JunB augments tumor angiogenesis and invasion." (PMID 32382040, 2020). "As suggested in murine model, ALK promotes the expression of activator protein 1 family members JUN and JUNB, which subsequently promote tumor dissemination through PDGFRB regulation." (PMID 32637355, 2020). "AP-1 proteins are primarily considered to be oncogenic but JunB, Fra-1 and Fra-2, have been shown to have tumor-suppressor activity." (PMID 33344262, 2020). "Using as threshold value the mean intensity of JUNB in normal PBMCs, 65% (13 out of 20) of the patients with detectable tumor cells in their blood harbored CTCs positive for JUNB." (PMID 31370904, 2019). "C-Fos forms complexes with cJun and JunB and bind to PD-1 promoter and thus upregulates PD-1 expression in infiltrating T-cells, resulting in attenuated anti-tumor response in this animal model." (PMID 31340499, 2019). "In summary, our results underscore the JunB role in the reinstitution of skin homeostasis during wound repair and tumor progression through tight regulation of epidermal progenitors and their differentiated progeny." (PMID 30143626, 2018). "Down-regulation of JUNB in tumour metastases (relative to primary tumours) is common to many human cancers." (PMID 30566430, 2018). "Control, c-Jun, or JunB shRNA–expressing L-428 cells were injected into immunocompromised mice and tumour growth was examined." (PMID 30375407, 2018). "Tumours formed from cells with decreased c-Jun or JunB expression were significantly reduced in size and weight compared to tumours formed from control shRNA–expressing cells." (PMID 30375407, 2018). "Depletion of JUN and JUNB or disruption of TAK1-RELA signaling blocked the cytokine-mediated induction of MMP9 in tumor cells." (PMID 28423685, 2017). "Depletion of JUN and JUNB or RELA in tumor cells blocked the cooperative induction of MMP9 by the cytokines." (PMID 28423685, 2017). "While initial observations suggested that c‐Jun acts mainly as an oncogene and JunB as a tumor suppressor, this model is being challenged in light of new findings." (PMID 28776955, 2017). "In situ examination of tumor tissues for expression of JunB, JunD, and c‐Fos by immunohistochemical analysis also confirmed presence of the AP‐1 members but their expression varied in HPV‐positive and HPV‐negative tissues on case to case basis." (PMID 28155253, 2017). "The mouse model was also used to confirm the role of JunB knockout in tumor metastasis in this study." (PMID 26754630, 2016). "While there is a great deal of evidence suggesting AP-1 supports tumor growth, there are also indications that JunB can act as a tumor suppressor in certain contexts." (PMID 24743777, 2014). "JUNB expression in knockout tumors was low but detectable, due to about 10–20% of stromal contamination estimated on the basis of histochemically stained tumor sections." (PMID 25013898, 2014). "Tumor formation in Ras-activated cancer cells is inhibited by overexpression of JunB, an effect that requires the JunB transactivation domain." (PMID 23762562, 2013).